RAPGEF5 (Rap guanine nucleotide exchange factor 5)
Description:
Guanine nucleotide exchange factor (GEF) for RAP1A, RAP2A and MRAS/M-Ras-GTP. Its association with MRAS inhibits Rap1 activation.
Synonyms: MR-GEF; Repac; GFR; KIAA0277; MRGEF
Tractability: Antibody: its Gene Ontology location is reachable by antibodies, with medium confidence.
Gene: Protein-coding gene on chromosome 7 (22,118,236 to 22,357,154, reverse strand). Ensembl gene ENSG00000136237.
Subcellular location: Nucleus
Subcellular location (Human Protein Atlas): Nucleoplasm; Nuclear bodies
Gene Ontology:
Molecular function: GTP-dependent protein binding; guanyl-nucleotide exchange factor activity; protein binding
Biological process: nervous system development; Rap protein signal transduction; Ras protein signal transduction; small GTPase-mediated signal transduction
Cellular component: nuclear body; nucleoplasm; nucleus; plasma membrane
Genetic constraint (gnomAD): Loss-of-function variants: 55 observed, 92.9 expected, observed/expected ratio (o/e) 0.59, 90% interval 0.48 to 0.74. The upper end of that interval is the gene's LOEUF score, 0.74, which puts it in group 3 of 6, group 1 being the genes least tolerant of losing a copy. Missense variants: 878 observed, 891.25 expected, observed/expected ratio (o/e) 0.99, 90% interval 0.93 to 1.04. Synonymous variants: 361 observed, 324.31 expected, observed/expected ratio (o/e) 1.11, 90% interval 1.02 to 1.21.
Homologues: Orthologues: macaque RAPGEF5 (99% identical), dog RAPGEF5 (95% identical), rat Rapgef5 (92% identical), guinea pig RAPGEF5 (86% identical), mouse Rapgef5 (85% identical), chimpanzee RAPGEF5 (82% identical), rabbit RAPGEF5 (75% identical), tropical clawed frog rapgef5 (70% identical), zebrafish rapgef5b (12% identical). Paralogues in human: RAPGEF4 (40% identical), RAPGEF3 (33% identical), RAPGEFL1 (25% identical), RAPGEF2 (21% identical), RAPGEF6 (19% identical), RAPGEF1 (16% identical), RASGRF1 (14% identical), RASGRF2 (14% identical), SOS2 (13% identical), RALGDS (13% identical), SOS1 (12% identical), RASGEF1B (12% identical), and 12 more.
Diseases named in the same sentence as RAPGEF5 in open-access papers:
RAPGEF5 is named in the same sentence as 25 diseases in open-access papers, as found by Europe PMC text mining. Sharing a sentence is not in itself a finding about the gene and the disease. The quoted sentences say what the papers report.
epilepsy (2 papers, 2022 to 2024). A brain disorder characterized by episodes of abnormally increased neuronal discharge resulting in transient episodes of sensory or motor neurological dysfunction, or psychic dysfunction. "The suggested role of RAPGEF5 in modulating β-catenin gene transcription and its association with epilepsy in the dog offers insight into the development of IE in the human." (PMID 39342265, 2024). "In humans and mice, the Aristaless Related Homeobox (ARX) gene has a polyalanine expansion mutation that is known to cause intellectual disability, epilepsy, and brain malformations and has a similar spatial expression profile as RAPGEF5 determined by in situ hybridization." (PMID 39342265, 2024). "Additionally, a potential role for RAPGEF5 in epilepsy has been implicated in humans and in mouse models of epilepsy suggesting a role for RAPGEF5 in the development of canine IE." (PMID 39342265, 2024). "Exploration of RAPGEF5 genetic variants in human epilepsy could reveal risk and generalized mechanistic underpinnings of IE and give further evidence of a role for nuclear translocation of β‐catenin in epileptogenesis." (PMID 39342265, 2024). "Further studies using genetically modified mice carrying the RAPGEF5 variant could yield additional insight into its role in epileptogenesis and provide a new animal model for epilepsy." (PMID 39342265, 2024). "In development, RAPGEF5 is continually expressed and in an animal model of induced epilepsy, RAPGEF5 is downregulated within areas generating fast ripples, which have been defined as an “electrophysiological signature that precedes the onset of epilepsy”." (PMID 35885906, 2022).
papillary thyroid cancer (2 papers, 2020 to 2023). "For instance, Circ-RAPGEF5 acts as a tumor promoter in papillary thyroid carcinoma by competitively binding miR-198, which represses FGFR1." (PMID 37705041, 2023).
renal cell carcinoma (2 papers, 2023 to 2025). "The genomic region on chromosome 7 is located near RAPGEF5, which regulates Rap proteins, and mutations in this gene have been linked to several diseases, including certain cancers such as renal cell carcinoma." (PMID 39898788, 2025). "Another study showed that Circ-RAPGEF5 was lowly expressed in renal cell carcinoma and exerted cancer-inhibiting effects in RCC via the miR-27a-3p/TXNIP pathway." (PMID 37705041, 2023).
bladder cancer (1 paper, 2025). "These loci included 14 previously reported bladder cancer-associated genes (eg, GSTM1 and NAT2) and 3 novel loci near MSX2, RAPGEF5, and MIPOL1 genes." (PMID 39898788, 2025).
diabetes (1 paper, 2025). "Diabetes aggravates post-MI remodeling via Rapgef5/Ing1-mediated apoptosis and proliferation, these findings highlight novel therapeutic targets for diabetic cardiovascular complications." (PMID 40162308, 2025). "Compared to the STEMI cohort, myocardial infarction (MI) patients with diabetes exhibited reduced expression of Rapgef5 and elevated expression of Ing1." (PMID 40162308, 2025). "Among these, two data points aligned with the RNA sequencing results, revealing downregulation of the Rapgef5 genes and upregulation of the Ing1 gene in cardiac tissues of patients with diabetes mellitus complicated by myocardial infarction." (PMID 40162308, 2025). "In addition, we have found that Rapgef5 and Ing1 are involved in diabetes-mediated cardiomyocyte apoptosis and proliferation following myocardial infarction." (PMID 40162308, 2025). "In addition, our extensive examination of human samples has conclusively demonstrated that diabetes significantly modulates the expression of genes (Rapgef5 and Ing1) within the cardiac tissue of individuals afflicted with STEMI, underscoring the intricate interplay between these conditions." (PMID 40162308, 2025).
Hypocalcemia (1 paper, 2020). An abnormally decreased calcium concentration in the blood. "Despite expression of RAPGEF5 in nervous tissue, the clinical signs in our affected foals of seizures were attributed to the severe hypocalcemia and were prevented with calcium supplementation." (PMID 32986719, 2020).
hypoparathyroid (1 paper, 2020). "Within this region, a nonsense variant (RAPGEF5 c.2624C>A,p.Ser875*) was significantly associated with the hypoparathyroid phenotype (Pallelic = 0.008)." (PMID 32986719, 2020). "This RAPGEF5 variant represents the first genetic variant for hypoparathyroidism identified in any domestic animal species." (PMID 32986719, 2020). "We definitively excluded these candidate genes in TB foals with familial hypoparathyroidism and instead identified a nonsense variant in RAPGEF5 c.2624C>A,p.Ser875* that significantly associated with the phenotype." (PMID 32986719, 2020). "In conclusion, we have identified a nonsense mutation in RAPGEF5 leading to hypoparathyroidism in neonatal TB foals." (PMID 32986719, 2020). "The mechanism by which RAPGEF5 loss-of-function leads to hypoparathyroidism remains uncertain." (PMID 32986719, 2020).
myocardial infarction (1 paper, 2025). Gross necrosis of the myocardium, as a result of interruption of the blood supply to the area, as in coronary thrombosis. "Based on the available search results, the mechanistic roles of Rapgef5 and Ing1 in diabetic myocardial infarction (MI) remain underexplored." (PMID 40162308, 2025).
temporal lobe epilepsy (1 paper, 2022). A localization-related (focal) form of epilepsy characterized by recurrent seizures that arise from foci within the temporal lobe, most commonly from its mesial aspect. "The ACTG risk haplotype falls 17,855 bases upstream of the Rap Guanine Nucleotide Exchange Factor 5 (RAPGEF5) gene, which has a role during neurogenesis and alterations in expression are associated with seizures such as temporal lobe epilepsy." (PMID 35885906, 2022).
thyroid cancer (1 paper, 2021). "Key regulators such as circular RNA RAPGEF5 have been associated with both RCC and thyroid cancer." (PMID 33808717, 2021).
tumor (7 papers, 2009 to 2025). "To further investigate the association between SAE1 and Circ-RAPGEF5, we performed the FISH assay in tissue microarrays containing 91 tumor tissues of patients with ICC." (PMID 37705041, 2023). "In our study, we analyzed 19 pairs of clinical samples of tumors and adjacent tissues and found that Circ-RAPGEF5 is highly expressed in ICC tumor tissues, suggesting a potential oncogenic role of Circ-RAPGEF5." (PMID 37705041, 2023). "In vitro and in vivo assays showed that Circ-RAPGEF5 promoted ICC tumor proliferation and metastasis, and inhibited apoptosis." (PMID 37705041, 2023). "Circ-RAPGEF5 was significantly upregulated in 19 ICC tumor tissues compared with adjacent paired normal tissues." (PMID 37705041, 2023). "The biological function of Circ-RAPGEF5 in tumor proliferation and metastasis was examined by a series of in vitro assays." (PMID 37705041, 2023). "We also demonstrated that Circ-RAPGEF5 is effective in the process of AKT SUMOylation, which has been reported to be strongly linked to tumor progression." (PMID 37705041, 2023). "The qRT-PCR analysis and FISH assay of tumor tissues showed that sh-Circ-RAPGEF5 lentivirus treatment resulted in a significant reduction in Circ-RAPGEF5 expression." (PMID 37705041, 2023). "Circ-RAPGEF5 promotes ICC tumor progression and SUMOylation by acting as a sponge for miR-3185 to stabilize SAE1." (PMID 37705041, 2023). "The tumor volume in the sh-Circ-RAPGEF5 treated group was significantly smaller than that in the control group." (PMID 37705041, 2023). "The regulation of Circ-RAPGEF5 and SAE1 could hold significant therapeutic value in the management, which was confirmed by the slowing of tumor growth due to our injection of Sh-Circ-RAPGEF5 lentiviral solution." (PMID 37705041, 2023). "The results showed that the depletion of Circ-RAPGEF5 significantly impaired the process of AKT SUMOylation and that this process could be rescued by SAE1, suggesting that Circ-RAPGEF5-mediated SUMOylation plays an important role in tumor formation and progression." (PMID 37705041, 2023). "Overall, we identified the circular RNA hsa_circ_0001681, termed Circ-RAPGEF5, which was highly expressed in ICC cell lines and tumor tissues." (PMID 37705041, 2023). "We further discovered that Circ-RAPGEF5 competitively binds miR-3185 to stabilize SAE1 from degradation, promote overall AKT SUMOylation, and induce tumor proliferation and migration." (PMID 37705041, 2023). "To investigate the role of Circ-RAPGEF5 in the progression of ICC in a model that closely mimics the clinical situation, we selected a patient-derived tumor xenograft (PDX) model for the in vivo experiments." (PMID 37705041, 2023). "Expression-based clustering of cells for the patient-1 tumor sample resolved two HGSOC cell clusters, with fusion RAPGEF5::AGMO evident in tumor cells largely clustered separately from cells expressing SMG7::CH507-513H4.1 and GS1-279B7.2::GNG4, potentially reflecting tumor heterogeneity." (PMID 40086881, 2025). "After 1 month of second-generation tumor growth, we started peri-tumor injections of lentivirus expressing sh-Circ-RAPGEF5 and negative control vector lentivirus every 2 days." (PMID 37705041, 2023). "They claimed that RAPGEF5 suppression could attenuate the transmembrane signaling receptor “fibroblast growth factor receptor 1 (FGFR1)” and thus suppress tumor growth by binding to miR-198, which sponged the 3′-UTR of FGFR1 via circRAPGEF5 targets in vitro." (PMID 36230649, 2022). "Sequencing of the patient-1 tumor sample yielded 497 total cells, with 92 cells (19%) identified as HGSOC cells, from which we identified only four somatic fusion transcripts: SMG7::CH507-513H4.1 (26 cells), RAPGEF5::AGMO (6 cells), NTN1::CDRT15P2 (five cells), and GS1-279B7.2::GNG4 (five cells)." (PMID 40086881, 2025).
tumor (continued). "Sequencing of the Patient-1 tumor sample yielded 497 total cells, with 92 cells (19%) identified as HGSOC cells, from which we identified only four somatic fusion transcripts: SMG7::CH507–513H4.1 (26 cells), RAPGEF5—AGMO (6 cells), NTN1--CDRT15P2 (5 cells), and GS1–279B7.2--GNG4 (5 cells)." (PMID 38464114, 2024).
cancer (5 papers, 2014 to 2025). A tumor composed of atypical neoplastic, often pleomorphic cells that invade other tissues. "Previous research has demonstrated that Circ-RAPGEF5 plays various roles in different types of cancers." (PMID 37705041, 2023). "Moreover, we implicate several of these gene hits not only in ccRCC for the first time (BHLHB3, CAMK1, CDH13, ENPP3, KCNJ2, KSR1, PLOD2, and TCF8), but also in a cancer model for the first time (CEP290, EFCAB3, PGBD5, RAPGEF5, SSPN, and TOX2)." (PMID 24979721, 2014).
infection (1 paper, 2023). The state of being infected such as from the introduction of a foreign agent such as serum, vaccine, antigenic substance or organism. "We used lentiviral infection to establish stably transfected sh-Circ-RAPEGEF5 and Circ-RAPGEF5 overexpression in RBE cells." (PMID 37705041, 2023).
neurological disorders (1 paper, 2024). "RAPGEF5 has also been associated with neurological disorders." (PMID 39342265, 2024).
RAPGEF5 also shares sentences with these, for which no sentence is quoted: Alzheimer disease (1 paper); bipolar disorder (1); brain malformations (1); breast carcinoma (1); cholangiocarcinoma (1); congenital stationary night blindness (1); COVID-19 (1); Intellectual disability (1); leukemia (1); psychosis (1); virus infection (1).